DHCR7 (7-dehydrocholesterol reductase)
Diseases named in the same sentence as DHCR7 in open-access papers (continued):
Sharing a sentence is not in itself a finding about the gene and the disease.
tumor (continued). "Next, we compared the expression of DHCR7 between GC tumor tissue and adjacent tissue in a public dataset." (PMID 36710342, 2023). "The tumor images and tumor volumes showed that DHCR7 overexpression significantly promoted tumor growth in vivo." (PMID 36710342, 2023). "Finally, it was observed that DHCR7 protein levels were significantly higher in CC cell lines than in non-tumor epithelial cell lines and that downregulation of DHCR7 protein negatively affected cell proliferation." (PMID 41596244, 2026). "Notably, the DHCR7 knockdown group combined with PD-1 inhibition (shDhcr7+PD-1) demonstrated more significant tumor growth suppression, with further reduced tumor volume and weight compared to the group with DHCR7 knockdown alone." (PMID 41246332, 2025). "Particularly, DHCR7 expression varied among different immune subtypes in various tumor types." (PMID 41198144, 2025). "In addition, we analyzed the differential expression of DHCR7 in tumor, normal, and metastatic tissues with TNMplot.com." (PMID 41198144, 2025). "Importantly, tumor cells expressing HMGCR/DHCR7 were enriched not only for cholesterol biosynthesis signatures but also for E2F target genes and G2/M checkpoint regulators." (PMID 41249736, 2025). "Altogether, our data suggest that, mechanistically, TGF-β1 activates MEK/ERK1/2 signaling, which in turn phosphorylates SREBP2 and enhances expression of enzymes involved in cholesterol synthesis, including DHCR7, which positively regulates tumor-derived EV release." (PMID 39910665, 2025). "Notably, immunohistochemical analysis showed that both PROX1 and the cholesterol synthesis enzyme DHCR7 were highly expressed in the tumor tissue compared to the adjacent healthy muscle." (PMID 41249736, 2025). "The role of DHCR7 in tumors and the tumor microenvironment has been dissected." (PMID 40529212, 2025). "Notably, our results also demonstrated that DHCR7 influences immune cell infiltration and correlates with immune checkpoint markers, suggesting its pivotal role in tumor immunology." (PMID 41198144, 2025). "Additionally, we also observed that DHCR7 was significantly overexpressed in tumor epithelial cells." (PMID 40735323, 2025). "Quantitative analysis revealed that cell migration and invasion numbers decreased by approximately 60-70%, indicating that DHCR7 may play a critical role in tumor metastasis." (PMID 41246332, 2025). "Our study demonstrated that blocking DHCR7 in the human HCC cell line HepG2 attenuated tumor growth and malignization, indicating that inhibition of DHCR7 in the tumor and/or the tumor microenvironment can produce a strong therapeutic effect on alcohol-induced liver injury and HCC." (PMID 40529212, 2025). "At present, tumor-related immunomodulators have become an important method for BC treatment, and in this study, we found that DHCR7 expression is significantly correlated with the immunoinhibitor, immunostimulators, and MHC molecules, including CD96, CD48, and HLA-DPB1." (PMID 38526324, 2024). "In addition, DHCR7 has been shown to be an oncogene and its high expression regulates the proliferation, migration, and invasion as well as apoptosis of tumor cells, such as in bladder cancer and gastric cancer." (PMID 38526324, 2024). "In addition, DHCR7 expression was related to tumor-infiltrating lymphocytes (TILs), such as Act B cells, imm B cells and Tem CD8 cells." (PMID 38526324, 2024). "In addition, DHCR7 expression inversely correlated with tumor-infiltrating lymphocytes." (PMID 41596244, 2026). "However, expression levels of DHCR7 in tumor tissues were significantly lower than in normal tissues, implying that components of desmosterol in tumors may be lower than in normal tissues." (PMID 36008975, 2022). "Silencing DHCR7, the terminal enzyme in cholesterol biosynthesis, profoundly inhibited RMS cell proliferation in vitro, reduced colony formation, and suppressed tumor growth in xenograft models." (PMID 41249736, 2025).
tumor (continued). "This strategy targets 7‐dehydrocholesterol reductase (DHCR7) in GSM using a degradable NR carrier to inhibit cholesterol biosynthesis and reduce the cholesterol supply from GSM to tumor cells, thereby limiting tumor cell survival and proliferation." (PMID 40995646, 2025). "Partial Dhcr7 deletion produced the most profound effect on tumorigenesis in DEN/HFD + EtOH-fed Dhcr7+/– mice, as shown by reduced tumor number, diameter, and expression of AFP and YAP, and phospho-STAT3." (PMID 40529212, 2025). "Previous studies have shown that a complex formed by EBP and DHCR7 called cholesterol epoxide hydrolase (CHEH) removes toxic cholesterol epoxides and promotes the growth of tumor cells." (PMID 36710342, 2023). "ChEH is a dimer of 7-dehydrocholesterol reductase (DHCR7) and 3β-hydroxysteroid-Δ8-Δ7-isomerase (D8D7I), and acts as a high affinity binding site for the anti-tumour drug tamoxifen." (PMID 27068984, 2016). "Relative expression levels of the eight genes of interest (AZGP1, BIRC5, DHCR7, IL6ST, MGP, RBBP8, STC2, and UBE2C) were compared between paired whole tissue sections and tumor-enriched specimens." (PMID 25218890, 2014). "Impaired DHCR7 activity may lead to 7‐DHC accumulation, increasing oxidative stress and genomic instability, thereby driving tumor initiation." (PMID 41198144, 2025). "We analyzed the differences between DHCR7 positive and DHCR7 negative epithelial cells in tumor tissues and identified highly expressed genes for GO and KEGG enrichment analyses." (PMID 40735323, 2025). "Similarly, DHCR7 (cholesterol biosynthesis), DDIT4 (mTOR regulation under stress), HNRNPAB (RNA splicing), and SLC39A8 (zinc signaling) all reflect well-documented mechanisms of tumor growth or adaptation." (PMID 40941703, 2025). "However, 27HC supplementation neutralized the inhibition of lung metastasis by DHCR7 knockdown, whereas the injection of the CYP27A1 inhibitor GW297X in cells overexpressing TMEM147 restrained tumor progression and metastasis, and supplementation with 27HC offset the effect of GW297X." (PMID 37891677, 2023). "However, based on these results it is not possible to distinguish whether DHCR7 silencing affected mainly tumor engraftment or tumor proliferation and growth." (PMID 41249736, 2025). "Therefore, DHCR7 and 7-DHC may be potential targets for tumor treatment." (PMID 40528239, 2025). "DHCR7 and HMGCR were broadly expressed across all malignant cell clusters, with no specificity for tumor subtype or anatomical origin." (PMID 41249736, 2025). "The combination of inhibitors with the cytotoxic drugs led to a significant decrease in tumor cell viability when compared to the chemotherapeutic treatment in the absence of the MEK and DHCR7 inhibitors." (PMID 39910665, 2025). "High expression of HMGCR and DHCR7 correlates with worse overall survival, and single-cell RNA-seq analyses demonstrate broad expression of genes of this pathway across RMS subtypes, irrespective of tumor origin." (PMID 41249736, 2025). "Interestingly, tumor diameters were also reduced in DEN/pair-fed and DEN/chow-fed Dhcr7+/– mice, demonstrating that suppression of Dhcr7 decreases HCC in steatotic and non-steatotic livers." (PMID 40529212, 2025). "Conversely, DHCR7 upregulation may enhance Hh signaling by reducing 7‐DHC, promoting tumor progression in triple‐negative breast cancer." (PMID 41198144, 2025).
infection (12 papers, 2009 to 2025). The state of being infected such as from the introduction of a foreign agent such as serum, vaccine, antigenic substance or organism. "Along these lines, perturbation of the flux due to supplementation of the cholesterol precursor 7-dehydrocholesterol or deficiency of its synthesizing enzyme 7-dehydrocholesterol reductase (DHCR7) augmented IFN-β production upon infection." (PMID 40098954, 2025). "We demonstrated that the expression of DHCR7, the terminal enzyme of cholesterol biosynthesis, was upregulated following infection." (PMID 39490926, 2024). "Our data showed that inhibited DHCR7 with AY9944 significantly reduced T. gondii replication, which indicated DHCR7 had an important role in infection." (PMID 39490926, 2024). "qRT-PCR analysis showed that DHCR7, SCD, and HMGCR mRNA levels were significantly increased in moDCs infected with ZIKV-EGFP-BeH819015 or ZIKV PRVABC59 compared with Mock and ZIKV− moDCs, as was observed following infection with ZIKV SD001." (PMID 36097162, 2022). "By contrast, infection was not hampered when mycelial plugs were inoculated and this is indicative of an indirect role for DHCR7 in pathogenicity." (PMID 35382565, 2022). "Furthermore, inhibition of DHCR7 by Tamoxifen resulted in a significant increase of IFN‐β mRNA level in macrophages with Poly (I:C) stimulation, which confirms that DHCR7 is an important regulator of IFN‐I transcription throughout an infection course." (PMID 37096860, 2023). "Moreover, treatment with BM 15766, an inhibitor of 7-dehydrocholesterol reductase (the enzyme catalyzing the last step of de novo cholesterol synthesis), failed to alter infection-induced lipid droplet accumulation." (PMID 30161232, 2018).
neurodevelopmental disorder (6 papers, 2014 to 2025). A behavioral and cognitive disorder with onset during the developmental period that involves impaired or aberrant development of intellectual, motor, or social functions. "We also examined hippocampal expression of Dhcr7 (encoding 7-dehydrocholesterol reductase, P < 0.05 in the microarray analysis) given that this gene had previously been implicated in neurodevelopmental disorders, and that its deficiency had been implicated in altered serotonergic function." (PMID 24602487, 2014).
autosomal recessive disease (3 papers, 2016 to 2025). Autosomal recessive form of disease. "Homozygous or compound heterozygous mutations in DHCR7 result in Smith–Lemli–Opitz (SLOS) syndrome, which is an autosomal recessive disease." (PMID 29458409, 2018).
DHCR7 also shares sentences with these, for which no sentence is quoted: genetic disease (5 papers); Intellectual disability (5); Insulin resistance (3); lung carcinoma (3); Adrenal insufficiency (2); melanoma (2); Metabolic disorders (2); Micrognathia (2); prostate carcinoma (2); Rett syndrome (2); rheumatoid arthritis (2); -Syndromic (1); 3-beta hydroxysteroid dehydrogenase deficiency (1); acute coronary syndrome (1); adenoma (1); arachnoid cyst (1); Atrophy (1); autism spectrum disorder (1); B-cell non-Hodgkin lymphoma (1); bipolar disorder (1); cataract (1); cervical adenocarcinoma (1); congenital malformation syndromes (1); Conradi–Hunermann syndromes (1); craniosynostosis (1); cryptorchidism (1); deficient (1); desmosterolosis (1); Ellis-van Creveld syndrome (1); familial breast cancer (1).
A further 40 diseases each share a sentence with DHCR7 in 1 paper.